NOTCH4 (notch receptor 4)
Diseases named in the same sentence as NOTCH4 in open-access papers (continued):
Sharing a sentence is not in itself a finding about the gene and the disease.
colorectal cancer (11 papers, 2017 to 2024). A primary or metastatic malignant neoplasm that affects the colon or rectum. "Another study also confirmed an association between high levels of NOTCH4 and aggressive malignant colorectal cancer cell phenotype." (PMID 35136410, 2022). "We examined the genotypes of four germline SNPs residing in NOTCH1 - rs3124591, NOTCH2 - rs11249433, NOTCH3 - rs1043994, and NOTCH4 - rs3830041 to determine their association with breast and colorectal cancer risk in Saudi Arabian patients." (PMID 34257585, 2021). "In the present study, we evaluated for the first time the association of NOTCH1, rs3124591; NOTCH2, rs11249433; NOTCH3, rs1043994, and NOTCH4, rs3830041 SNPs with the susceptibility of breast and colorectal cancers in Saudi population." (PMID 34257585, 2021). "The upregulated NOTCH4 expression was closely associated with advanced stage of colorectal cancer." (PMID 32343052, 2020). "Nevertheless, we have little data on the clinical application of Notch4 protein expression in European patients with colorectal cancer, especially with colon adenocarcinoma." (PMID 37108670, 2023). "Notch3 and Notch4 expressions were significantly higher in colorectal cancers compared to normal and adenoma tissues (Notch3: normal vs. CRC, p=0.0052, adenoma vs CRC, p=0.0018; Notch4; normal vs. CRC, p=0.0046, adenoma vs. CRC, p=0.036)." (PMID 32211044, 2020). "In our cohort, Notch4 expression was significantly higher in colorectal cancers than normal (p=0.0046) as well as adenoma tissues (p=0.036), suggesting its involvement in CRC progression." (PMID 32211044, 2020). "NOTCH4 functions as a membrane receptor in regulating cell-fate determination, including cell differentiation, proliferation, and apoptosis in vertebrates and it is overexpressed in various types of cancer, including breast and colorectal cancer." (PMID 38789628, 2024). "In vitro functional experiments suggested that changing the expression level of NOTCH4 in colorectal cancer could significantly affect the proliferation and invasion of colorectal cancer cells." (PMID 37325053, 2023). "In this case-control study, TaqMan genotypic analysis of rs3124591 in NOTCH1 and rs3820041 in NOTCH4 did not exhibit association with breast as well as colorectal cancers." (PMID 34257585, 2021). "We observed overexpression of Notch4 in 56% of colorectal cancers." (PMID 32211044, 2020). "In order to evaluate whether gender played any role in the association of NOTCH1-rs3124591, NOTCH2-rs11249433, NOTCH3-rs1043994, and NOTCH4-rs3830041 with colorectal cancers, the study subjects were grouped as males and females for counting the genotype and allele frequencies." (PMID 34257585, 2021). "Besides calculating fold-change expression of Notch pathway genes in adenomas and colorectal cancers relative to the adjacent normal tissues, we further calculated expression of Notch3 and Notch4 by the ΔCt method using GAPDH as reference gene in normal, adenoma, and cancer tissues." (PMID 32211044, 2020). "Aberrant NOTCH signaling promotes the development and progression of colorectal cancer and is partly driven by the overexpression of JAG1, a ligand of NOTCH4." (PMID 32751332, 2020).
breast tumor (10 papers, 2013 to 2025). "An mRNA transcript encoding the intracellular domain of NOTCH4 was detected in two human breast neoplasm lines." (PMID 26253105, 2015). "Collectively, these studies indicate Notch4 upregulation among the mechanisms promoting the resistance to the hormonal therapy in ER+ breast tumors and suggest its targeting as a potential strategy to overcome the relapsed disease." (PMID 34680255, 2021). "In fact, one of the Notch receptor paralogs, Notch4, was discovered via a mouse mammary tumor virus (MMTV) integration into the Notch4 locus, resulting in hyperactivated Notch signaling and breast tumors in mice." (PMID 30388742, 2018). "Our results show increased levels of Notch4 in the blood vessels of mouse and human breast tumor tissues." (PMID 23601498, 2013). "Furthermore, our results suggest that host Notch4 plays a role in the early emergence of MMTV-PyMT breast tumors following transplantation." (PMID 23601498, 2013). "To investigate the potential role of Notch4 in TNBC, we evaluated the prognostic value of Notch4 mRNA in a large online gene chip database of breast tumors from 1880 patients for overall survival (OS) and 4934 patients for recurrence-free survival (RFS) in Kaplan–Meier plotter." (PMID 37149651, 2023).
hepatocellular carcinoma (10 papers, 2013 to 2025). A malignant tumor that arises from hepatocytes. "Interestingly, recent studies showed that HBV X protein activated Notch signaling via Notch1/Notch4/Dll4 in HBV-associated hepatocellular carcinoma." (PMID 27800305, 2016). "HIF-1α upregulated the expression of Notch1, Notch3 and Notch4 via binding to the hypoxia response elements in their promoter regions in hepatocellular carcinoma cell lines." (PMID 34988077, 2021). "Ahn and colleagues found that Notch1 and Notch4 are markers for poor prognoses during hepatocellular carcinoma." (PMID 24386256, 2013). "Androgen receptor (AR) could directly target the circR7 host gene promoter to suppress circR7 formation, up‐regulate miR‐7‐5p, which might directly target the VE‐cadherin and Notch4 3′UTR to suppress VM formation in hepatocellular carcinoma." (PMID 39964093, 2025). "Similarly Notch4 has been considered as a candidate histochemical marker in identifying hepatocellular carcinoma." (PMID 29162408, 2019).
arteriovenous malformations (9 papers, 2009 to 2020). "Firstly, we checked for variants in ENG, NOTCH4, and TGFβR2 that are known to be involved in arteriovenous malformation development." (PMID 32560555, 2020). "Constitutively active endothelial NOTCH4 inhibitsEC apoptosis, and is associated with brain and lung arteriovenous malformations in mice, suggesting roles of NOTCH4 in EC survival and vascularintegrity." (PMID 32166015, 2020). "Up-regulation of Notch4 was observed in the endothelial cells in the arteriovenous malformations (AVMs) in mice." (PMID 24373503, 2013). "Our findings suggested that Notch 4, and more importantly, Notch 3, may play a role in the development and pathobiology of human arteriovenous malformations." (PMID 25846406, 2015). "Interestingly, one of these transgenes, Tg(tetO-Notch4*)1Rwng (MGI:5502689), contains DNA encoding amino acids 1411–1964 of Notch4 placed under the control of the tetracycline response element and is used to model arteriovenous malformations of the human brain (DOID:0060688)." (PMID 30833663, 2019).
rheumatoid arthritis (9 papers, 2011 to 2024). A chronic, systemic autoimmune disorder characterized by inflammation in the synovial membranes and articular surfaces. "Different studies have related certain NOTCH4 polymorphisms with the development of inflammatory processes associated with autoimmune diseases, including rheumatoid arthritis or alopecia areata." (PMID 34925319, 2021). "Genetic variants in NOTCH4 also have been previously associated, independently from HLA genes or alleles, with other autoimmune disorders like diabetes type 1, rheumatoid arthritis and alopecia areata." (PMID 21779181, 2011). "NOTCH4 is also associated with alopecia areata and rheumatoid arthritis." (PMID 38943194, 2024). "In addition, previous studies reported that NOTCH4 was associated with multiple autoimmune diseases, including Crohn's disease, systemic scleroderma, rheumatoid arthritis, and ulcerative colitis." (PMID 33134369, 2020). "In synovial fibroblasts of patients with rheumatoid arthritis Tumor Necrosis Factor (TNF) drives the expression of Jagged-2, Notch-1, and Notch-4, along with a hallmark of Notch activation, the Notch intracellular domain (NICD) nuclear translocation." (PMID 38314334, 2024). "Multiple genetic association studies have associated NOTCH4 with rheumatoid arthritis (RA)." (PMID 34039391, 2021).
prostate carcinoma (8 papers, 2012 to 2024). A carcinoma that arises from epithelial cells of the prostate gland. "In prostate cancer, Notch 4′s effects on prostate cancer cell proliferation, growth, EMT, migration and invasion were shown to be dependent on the NFkB pathway." (PMID 32575680, 2020). "Collectively, these results indicated that SFN treatment resulted in cleavage of Notch1, Notch2, and Notch4 in both androgen-independent and androgen-responsive human prostate cancer cells." (PMID 22970326, 2012). "A total of 20 genes are involved in these intra-category multimorbid relationships and are mainly related to the human leukocyte antigen (HLA) complex (such as HLA-DQA1 and HLA-DRB1), histone clusters (such as HIST1H1B and HIST1H2AJ), and tumors (such as TERT and NOTCH4 for prostate cancer)." (PMID 34225788, 2021). "Therefore, when Notch 4 was silenced, this led to inhibition of important hallmarks of prostate cancer cells, which was shown to be dependent on the NFkB pathway." (PMID 32575680, 2020). "The present study used cultured human prostate cancer cells (PC-3, LNCaP, and LNCaP-C4-2B), and dorsolateral prostate tissues from control and SFN-treated TRAMP mice to determine the role of Notch1, Notch2, and Notch4 in anticancer effects of SFN." (PMID 22970326, 2012). "Specifically, knockdown of Notch1, Notch2 or Notch4 has no impact at all or only marginal effect on SFN-mediated inhibition of prostate cancer cell migration." (PMID 22970326, 2012).
non-small cell lung carcinoma (7 papers, 2018 to 2025). A group of at least three distinct histological types of lung cancer, including non-small cell squamous cell carcinoma, adenocarcinoma, and large cell carcinoma. "Thus, NOTCH4 underexpression increases disease-free survival in long squamous cell carcinoma, and mutations in the NOTCH4 gene appear to lead to improved survival rates in non-small-cell lung cancer." (PMID 37509254, 2023). "In patients with Non-Small Cell Lung Cancer (NSCLC), Notch4 expression was positively associated with tumour size, lymph node metastasis (LNM), distal metastasis (DM), and depth of invasion (T)." (PMID 37108670, 2023). "The NOTCH4 expression level was especially higher in non-small-cell lung cancer tissues than in the NC tissues, related to the tumor size and TNM stage." (PMID 34211553, 2021). "The role of NOTCH4 in non-small cell lung cancer progression remains to be fully defined." (PMID 39595659, 2024). "The correlation between VM, or Notch4, or DLL4, or KAI1/CD82 and clinicopathological characteristics in non-small cell lung cancer." (PMID 30593175, 2018). "In the article “Evaluation of the correlation of vasculogenic mimicry, Notch4, DLL4, and KAI1/CD82 in the prediction of metastasis and prognosis in non-small cell lung cancer”, the structure presented as VM could be considered a blood lake." (PMID 40786517, 2025). "In a retrospective study titled “Evaluation of the correlation of vasculogenic mimicry, Notch4, DLL4, and KAI1/CD82 in the prediction of metastasis and prognosis of the course of non-small cell lung cancer” a cohort of 189 patients was analyzed to assess the impact of VM on OS." (PMID 40786517, 2025).
psoriasis (7 papers, 2009 to 2025). An autoimmune condition characterized by red, well-delineated plaques with silvery scales that are usually on the extensor surfaces and scalp. "Further stratified association analysis illustrated that HLA-C∗06:02 and NOTCH4:G511S contribute to the family aggregation of psoriasis, and BTNL2:R281K specifically confers risk for SP." (PMID 33134369, 2020). "For those specific variants in PFH or SP, we found that NOTCH4:G511S (OR = 1.24, P = 4.26 × 10−3) contributes to the familial clustering of psoriasis." (PMID 33134369, 2020). "NOTCH4 has been predominantly associated with neuropsychiatric disorders; little information is available on the association with psoriasis." (PMID 22125590, 2011). "When we conditioned on HLA-C and NOTCH4, we observed an independent association at HLA-B amino acid position 67 (B-Y67C, OR = 1.80, P = 5.45 × 10−11), which was previously reported to be associated with psoriasis in both European and Han Chinese populations." (PMID 33134369, 2020). "The co-localization analysis revealed genes positively associated with the risk of psoriasis, including HLA-DOB, NOTCH4, and VARS2." (PMID 40861805, 2025). "Our stratified analysis suggested that NOTCH4:G511S and HLA-C∗06:02 contribute to the familial clustering of psoriasis." (PMID 33134369, 2020). "Our results suggested that HLA-C∗06:02 and NOTCH4:G511S may independently contribute to the familial clustering of psoriasis." (PMID 33134369, 2020). "We found NOTCH4:G511S and HLA-C∗06:02 could partially explain why patients with a family history have an earlier onset of psoriasis and more frequent enthesitis and other autoimmune diseases." (PMID 33134369, 2020). "Therefore, NOTCH4:G511S and HLA-C∗06:02 may independently contribute to the family clustering of psoriasis based on our two hypothetical models." (PMID 33134369, 2020). "In addition, we found that SNPs from several non-HLA genes including rs2251396, rs2523454 and rs12175589 in MICA, rs7770216 in LOC729816, rs511027 in NOTCH4, rs9257483 in OR12D2 and 9262167 in IER3 were associated with psoriasis in multiple regression analyses." (PMID 22125590, 2011). "In addition to classical HLA genes such as HLA-C, HLA-B and HLA-DQA2, we also find association of non-HLA genes in the MHC region such as POU5F1, NFKBIL1, NOTCH4, MICA, IER3 and OR12D2 with psoriasis." (PMID 22125590, 2011).
sarcoidosis (7 papers, 2012 to 2023). Sarcoidosis is a multisystemic disorder of unknown cause characterized by the formation of immune granulomas in involved organs. "NOTCH4 was identified as a sarcoidosis-associated risk and severity gene in AA populations, and HLA-DRB1 SNPs as risk/severity SNPs for progressive sarcoidosis in European descent subjects and disease susceptibility in African descent subjects." (PMID 38390497, 2023). "Previous work has found associations in African Americans carrying NOTCH4-associated variants with sarcoidosis, which involves the formation of inflammatory cells (granulomas) in the body, primarily in the lungs." (PMID 37415598, 2023). "Other genes associated with immune regulation of sarcoidosis, including NOTCH4, TNFα, NOD2, and ANXA11, were also detected by GWAS analysis in different races." (PMID 35860586, 2022). "The protein interactive network identified an important correlation between HBEGF and NOTCH4, a key regulator of T cell activity and the branching angiogenesis associated with sarcoidosis." (PMID 36388923, 2022). "These included MMP9, a matrix metalloproteinase strongly associated with lung injury and fibrosis, and NOTCH4, an important regulator of inflammation and lung remodeling previously implicated in sarcoidosis." (PMID 36388923, 2022). "Supporting this association, SNPs in NOTCH4 have been reported as a sarcoidosis-associated locus in genome-wide associated study in African Americans." (PMID 33276795, 2020). "We identified significant association between sarcoidosis and a previously unreported locus (NOTCH4) in our AA datasets." (PMID 22952805, 2012). "While further studies are needed to define the role of NOTCH4 in the specific pathogenesis of sarcoidosis, a novel association to this gene is supported by previous expression and disease studies." (PMID 22952805, 2012). "We identified a novel sarcoidosis-associated locus, NOTCH4, that reached genome-wide significance in the combined AA samples (rs715299, PAA-meta = 6.51×10−10) and demonstrated the independence of this locus from others in the MHC region in the same sample." (PMID 22952805, 2012). "A GWAS study identified NOTCH4 SNPs associated with sarcoidosis severity in African Americans." (PMID 36388923, 2022). "A rare SNP in NOTCH4 (rs715299, MAF<0.00003) is associated with sarcoidosis in ADs and EDs independently from others in the MHC region." (PMID 38390497, 2023). "On the other hand, we confirmed downregulation of NOTCH4 expression to be exclusively present in lung sarcoidosis." (PMID 33276795, 2020). "In that study, subsequent conditional analyses revealed four additional independent variants (SNPs rs146146117 HLA-DQA1, rs9461776 HLA-DRB1, rs715299 NOTCH4, and rs9272320 HLA-DQA1) associated with sarcoidosis risk in the HLA class II region at the suggestive GWA significance threshold." (PMID 24663488, 2014). "This study corroborates previous genomic markers suggested for sarcoidosis such as STAB1, HBEGF, FABP4 and NOTCH4, with HBEGF and NOTCH4 only expressed in lung granulomas." (PMID 33276795, 2020).
autoimmune disease (6 papers, 2011 to 2023). A disorder resulting from loss of function or tissue destruction of an organ or multiple organs, arising from humoral or cellular immune responses of the individual to their own tissue constituents. "The segregation of this rare variant across three generations in a family argues that the variety of non-coding polymorphisms seen in autoimmune disease at the chromosome 6p21 genomic locus are affecting expression of the NOTCH4 gene." (PMID 27829420, 2016). "The NOTCH4 locus has previously been associated, independently from the HLA, with other autoimmune disorders including ulcerative colitis, rheumatoid arthritis, and alopecia areata and age-related macular degeneration." (PMID 27829420, 2016). "For example, MCODE1 was associated with autoimmune diseases, MCODE2 was associated with legionellosis and antigen processing presentation, and MCODE3 was associated with negative regulation of NOTCH4 signaling." (PMID 36755318, 2023). "HLA-C∗06:02 and NOTCH4:G511S could partially explain why patients with PFH have a stronger genetic predisposition, more complex phenotypes, and more frequent other autoimmune diseases." (PMID 33134369, 2020). "Polymorphisms affecting expression of NOTCH4 have been implicated in a broad array of autoimmune diseases independent of their proximity to the HLA locus on chromosome 6p21." (PMID 27829420, 2016).
leukemia (6 papers, 2011 to 2023). A malignant (clonal) hematologic disorder, involving hematopoietic stem cells and characterized by the presence of primitive or atypical myeloid or lymphoid cells in the bone marrow and the blood. "An association of a Notch 4 intronic SNP and the risk of disease relapse in patients with leukemia after transplantation was found in a genomic analysis on 141 patients with leukemia and their respective hematopoietic stem cell donors." (PMID 33374160, 2020). "WES identified all 14 known Notch1 mutations, and also uncovered somatic mutations in the Notch pathway genes Notch4 and Cntn1 in two additional leukemias." (PMID 31199785, 2019). "Excluding the SYNE1, NOTCH4, and CHEK1 genes, all others are well known leukemia/lymphoma cancer genes with a tier 1 category in the Cancer Gene Census database." (PMID 34573308, 2021). "More studies are needed to clarify how Notch 3 participates in hematological malignancy pathogenesis, while the lack of compelling data on Notch 4 possibly means a less direct or a non-canonical involvement in leukemia and lymphoma." (PMID 33374160, 2020).